CHSY3 (chondroitin sulfate synthase 3)
Description:
Catalytic component of CHSY1-CHPF2 and CHSY1-CHPF chondroitin sulfate synthase complexes. Has both beta-1,3-glucuronic acid and beta-1,4-N-acetylgalactosamine transferase activity. Transfers glucuronic acid (GlcUA) from UDP-GlcUA and N-acetylgalactosamine (GalNAc) from UDP-GalNAc to the non-reducing end of the elongating chondroitin polymer. Specific activity is much reduced compared to CHSY1.
Synonyms: ChSy-2; CHSY2; CSS3
Tractability: Antibody: UniProt predicts a signal peptide or a membrane-spanning region.
Gene: Protein-coding gene on chromosome 5 (129,904,465 to 130,186,634, forward strand). Ensembl gene ENSG00000198108.
Subcellular location: Golgi apparatus, Golgi stack membrane
Pathways (Reactome):
Metabolism: CS-GAG biosynthesis
Gene Ontology:
Molecular function: glucuronosyl-N-acetylgalactosaminyl-proteoglycan 4-beta-N-acetylgalactosaminyltransferase activity; N-acetylgalactosaminyl-proteoglycan 3-beta-glucuronosyltransferase activity; acetylgalactosaminyltransferase activity
Biological process: chondroitin sulfate proteoglycan biosynthetic process
Cellular component: Golgi membrane; Golgi apparatus; Golgi cisterna membrane
Genetic constraint (gnomAD): Loss-of-function variants: 27 observed, 41.74 expected, observed/expected ratio (o/e) 0.65, 90% interval 0.48 to 0.89. The synonymous counts are far from expectation, so gnomAD's model fits this gene poorly and the ratio says little. Missense variants: 761 observed, 767.63 expected, observed/expected ratio (o/e) 0.99, 90% interval 0.93 to 1.05. Synonymous variants: 359 observed, 295.61 expected, observed/expected ratio (o/e) 1.21, 90% interval 1.11 to 1.33.
Homologues: Orthologues: chimpanzee CHSY3 (99% identical), macaque CHSY3 (99% identical), pig CHSY3 (95% identical), dog CHSY3 (95% identical), rabbit CHSY3 (94% identical), mouse Chsy3 (91% identical), rat Chsy3 (91% identical), tropical clawed frog chsy3 (72% identical), zebrafish chsy3 (65% identical), Drosophila melanogaster Chsy (37% identical), Caenorhabditis elegans sqv-5 (33% identical). Paralogues in human: CHSY1 (62% identical), CHPF2 (19% identical), CHPF (19% identical), CSGALNACT1 (18% identical), CSGALNACT2 (18% identical), B4GALNT3 (17% identical), B4GALNT4 (16% identical).
Diseases named in the same sentence as CHSY3 in open-access papers:
CHSY3 is named in the same sentence as 24 diseases in open-access papers, as found by Europe PMC text mining. Sharing a sentence is not in itself a finding about the gene and the disease. The quoted sentences say what the papers report.
gastric cancer (3 papers, 2023 to 2025). A primary or metastatic malignant neoplasm involving the stomach. "Overall, we demonstrated that CHSY3 expression in gastric cancer is associated with immune infiltration." (PMID 38812506, 2024). "High CHSY3 expression was associated with poor patient prognosis, and the experiments showed that CHSY3 expression regulated the proliferation and migration of gastric cancer cells, and increased the infiltration of tumor-associated macrophages." (PMID 38812506, 2024). "Here, we showed that high CHSY3 expression promotes proliferation in gastric cancer (GC) cells and is associated with poor prognosis in GC patients." (PMID 38812506, 2024). "We found that CHSY3 could promote the progression and migration of gastric cancer cells through cellular experiments, but we found that the expression of CHSY3 was associated with the infiltration of tumor-associated macrophages." (PMID 38812506, 2024). "However, only recent reports have shown that CHSY3 expression is associated with the development and metastasis of gastric cancer." (PMID 38812506, 2024). "We analyzed and verified gastric cancer tissue samples and found that high CHSY3 expression was associated with poorer prognosis and could be an independent risk factor for gastric cancer development." (PMID 38812506, 2024). "In vitro and in vivo studies confirm that CHSY3 enhances gastric cancer cell proliferation, migration and invasion." (PMID 40313244, 2025). "In conclusion, these data suggest that CHSY3 can promote gastric cancer development and underscore its potential relevance as a prognostic biomarker for gastric cancer treatment." (PMID 38812506, 2024). "We analyzed the immunohistochemistry data of 150 gastric cancer patients to determine the clinicopathological and survival significance of CHSY3." (PMID 38812506, 2024). "We found that the expression of CHSY3 was associated with pathological TNM stage, lymph node metastasis, and LVI in gastric cancer patients." (PMID 38812506, 2024). "The present study was thus developed to explore the mechanistic importance of CHSY3 as a regulator of gastric cancer." (PMID 37461041, 2023). "In summary, knockdown of CHSY3 impairs the proliferation, migration, and invasion of gastric cancer cells." (PMID 37461041, 2023). "The results of this study suggest that CHSY3 is an important regulator of gastric cancer progression, highlighting its promise as a therapeutic target for gastric cancer." (PMID 37461041, 2023). "In this study, we revealed the function and expression of CHSY3 in gastric cancer." (PMID 38812506, 2024). "In this paper, the role of CHSY3 in gastric cancer was shown to be related to the malignant phenotype of gastric cancer through pathological results and cellular experiments, and we also found that the expression of CHSY3 in gastric cancer was related mainly to the infiltration of macrophages." (PMID 38812506, 2024). "Notably, in both in vitro and in vivo experiments, modulation of CHSY3 expression adequately regulates the proliferative, migratory, and invasive capabilities of gastric cancer cells." (PMID 37461041, 2023). "The glycosyltransferase CHSY3 is a CHSY family member, yet its importance in the context of gastric cancer development remains incompletely understood." (PMID 37461041, 2023).
intervertebral disc degeneration (2 papers, 2021 to 2023). "The activation of Yap1, which is a transcriptional coactivator as well as a negative regulator of the Hippo pathway, and is involved in intervertebral disc degeneration, was mainly affected in nucleus pulposus cells from Chsy3-deficient mice." (PMID 34901009, 2021). "Chsy3-deficient mice showed a shorter body length than the wild-type after 4 weeks old, a reduction of CS in disc tissues, and intervertebral disc degeneration such as a narrowed disc height, loss of the nucleus pulposus, and unclear demarcation between the nucleus pulposus and annulus fibrosus." (PMID 34901009, 2021).
lymph node metastasis (2 papers, 2023 to 2024). "In addition, correlations between CHSY3 expression and GC patient clinicopathological characteristics were examined, revealing higher levels of CHSY3 expression to be correlated with depth of invasion, advanced TNM stage, and lymph node metastasis." (PMID 37461041, 2023).
Stomach Adenocarcinoma (2 papers, 2022 to 2023). "CHSY3 gene expression in stomach adenocarcinoma (GC) and healthy tissues from the TCGA database were analyzed, demonstrating increased expression of CHSY3 in tumors compared to normal tissues." (PMID 37461041, 2023).
colorectal tumor (1 paper, 2015). "CHSY3 is generally expressed at insignificant levels, but is higher in colorectal tumor cells compared to healthy tissues." (PMID 26515597, 2015).
laryngeal carcinoma (1 paper, 2010). Carcinoma that arises from the laryngeal epithelium. "In our study, the most clear observations in laryngeal cancer were the significant decrease of CHSY3, CHST3 and D4ST1, and the significant increase of DSE." (PMID 20929582, 2010).
uterine corpus endometrial carcinoma (1 paper, 2024). A endometrial carcinoma (disease) that involves the body of uterus. "Furthermore, the highest alteration frequency of CHSY3 (6%) was observed in uterine corpus endometrial carcinoma patients with “mutation”." (PMID 38812506, 2024).
cancer (7 papers, 2015 to 2024). A tumor composed of atypical neoplastic, often pleomorphic cells that invade other tissues. "Several tumor-infiltrating lymphocytes are independent predictors of cancer survival; thus, we investigated the association between CHSY3 expression and immune infiltration levels in GC patients." (PMID 38812506, 2024). "Like in their study, in which we evaluated the expression of CHSY3 via TIMER, TCGA and other databases, we found that CHSY3 was abnormally highly expressed in a variety of cancers, and compared with paraneoplastic tissues, CHSY3 was more highly expressed in tumors." (PMID 38812506, 2024). "However, only a few studies have focused on CHSY3 in cancer." (PMID 35571047, 2022). "The similarly up-regulated chondroitin synthases (CHSY1, CHSY3, and CHPF) in both cancer tissue and human placenta indicate an important role of the proteoglycan CS chains length for Plasmodium falciparum VAR2CSA protein binding." (PMID 34966741, 2021). "We found that three chondroitin synthases (CHSY1, CHSY3, and CHPF) were upregulated in both cancer tissue and placenta, indicating an important role of ofCS chains length for VAR2CSA binding." (PMID 34966741, 2021). "It has been reported that co-expression of CHSY3 with CHPF confers a chondroitin sulfate polymerization activity, and chondroitin sulfate plays an important role in cancer biology." (PMID 26515597, 2015). "The relationship between CHSY3 and the immune microenvironment in GC was studied via the TCGA database, and the results of the R package “GSVA” demonstrated that CHSY3 was positively correlated with different immune cells in these cancers." (PMID 38812506, 2024). "We found that JW-7-52-1, GW843682, and MG-132 may be effective as drugs for targeting CHST, CHSY3, and DSE, respectively, based on the Genomics of Drug Sensitivity in Cancer (GDSC) database." (PMID 35326589, 2022). "Three chondroitin synthases (CHSY1, CHSY3, and CHPF) were upregulated in both cancer and placenta, indicating the length of ofCS chains might be an important factor for VAR2CSA binding." (PMID 34966741, 2021).
tumor (6 papers, 2015 to 2024). "Immunohistochemistry and bioinformatic analysis revealed that CHSY3 expression was significantly positively correlated with tumor-associated macrophage (TAM) infiltration." (PMID 38812506, 2024). "High CHSY3 expression was associated with more advanced tumor stage, higher recurrence risk and worse survival." (PMID 38812506, 2024). "Similar results were obtained for tissue microarrays composed of tumors from 68 GC tissues and normal gastric tissue from 68 GC patients, and Kaplan–Meier analysis showed that higher levels of CHSY3 expression were similarly associated with poor prognosis in this group of GC tumor tissues." (PMID 37461041, 2023). "Therefore, additional investigations are needed to determine whether CHSY3 expression is associated with tumor outcome." (PMID 38812506, 2024). "Next, we explored CHSY3 co-expression networks using the LinkedOmics database to verify the potential function of CHSY3 in tumor tissue." (PMID 38812506, 2024). "Furthermore, the relationship between the high/low expression of CHSY3 and immune cell infiltration was analyzed, and the results showed that the up-regulation of CHSY3 expression increased the infiltration level of various immune cells, especially tumor-associated macrophages." (PMID 38812506, 2024). "In recent years, the infiltration of immune cells in the tumor immune microenvironment has attracted increased attention, and we found that patients with high CHSY3 expression had worse OS." (PMID 38812506, 2024). "In conclusion, this study revealed that CHSY3 has a tumor-promoting effect on GC, suggesting a novel therapeutic strategy against this disease." (PMID 38812506, 2024). "CHSY3 upregulation was observed in GC tumor tissues, and patients expressing higher levels of this gene exhibited poorer prognostic outcomes." (PMID 37461041, 2023). "Further correlation analysis between the Tumor Immune Dysfunction and Exclusion (TIDE) score and the Immune Prognostic Score (IPS) suggests a compelling association with CHSY3 expression, thereby impairing the efficacy of immune-based therapies." (PMID 37461041, 2023). "The antineoplastic efficacy of CHSY3 inhibition in combination with αPD-L1 was evaluated in an MFC tumour model where mice were subjected to subcutaneous injection of tumour cells." (PMID 37461041, 2023). "CHSY3 levels were also significantly related to the composition of the tumor microenvironment, as evidenced by their significant correlation with immune, stromal, and ESTIMATE scores." (PMID 37461041, 2023). "Through additional analyses of 10 pairs of GC patient paracancerous and tumor tissues collected, the upregulation of CHSY3 in GC was further confirmed in an independent dataset." (PMID 37461041, 2023). "The similar increase of CHSY3 was observed in GC tumor tissues in comparison to paired paracancerous tissues." (PMID 37461041, 2023). "Additionally, CHSY3 was predominantly found in tumor tissues and showed higher abundance compared to matched adjacent tissues." (PMID 38812506, 2024). "We selected CHSY3 expression levels that were positively correlated with tumor purity." (PMID 38812506, 2024). "In subcutaneous tumor experiments in nude mice, tumor growth was significantly faster in nude mice injected with CHSY3 overexpressing HGC-27 cells than in controls, while tumor growth was significantly slower in nude mice injected with CHSY3 knockdown AGS cells than in controls." (PMID 37461041, 2023). "Furthermore, in vivo experiments have unequivocally demonstrated that the targeted inhibition of CHSY3, in combination with anti-PD-L1 therapy, significantly suppresses tumor growth." (PMID 37461041, 2023). "In addition, quantitative analysis of Western blot experiments demonstrated that CHSY3 expression was significantly higher in tumour tissues than in normal tissues in 7 out of 8 pairs of tissues." (PMID 35571047, 2022).
tumor (continued). "Therefore, given the high CHSY3 expression, the activation of the tumour mesenchyme inhibit numerous T-cells to infiltrate the tumour through the mesenchyme, resulting in an immune-evasion state." (PMID 35571047, 2022). "Finally, the immune-evasion potential of CHSY3 in STAD was assessed on the Tumor Immune Dysfunction and Exclusion (TIDE) website and immunohistochemical staining experiment." (PMID 35571047, 2022). "The ESTIMATE assessment of the TIME in STAD also revealed that the immune cell score and tumour stroma score were significantly higher in the high CHSY3 expression group than in the low CHSY3 expression group, while the tumour purity score demonstrated the opposite phenomenon." (PMID 35571047, 2022). "The purpose of staining was to observe the infiltration of CD3+ T cells, CD4+ T cells and CD8+ T cells in STAD tumour tissues and surrounding tissues to determine whether the high expression of CHSY3 in TIME is consistent with the characteristics of immune evasion." (PMID 35571047, 2022). "Subsequently, correlation analysis revealed that CHSY3 expression in GC was revealed to be significantly positively correlated with stromal, immune, and ESTIMATE scores, and negatively correlated with tumor purity." (PMID 37461041, 2023). "The ability of CHSY3 to regulate tumor was further assessed by CCK-8 assay and cloning assay, EDU assay, migration assay, invasion assay, and xenograft tumor model analysis." (PMID 37461041, 2023). "The prognostic value of CHSY3 in STAD was analysed through the biological aspects of CHSY3 in STAD, such as communal clinical follow-up survival data, methylation sites, tumour immune microenvironment (TIME) and immune cell surface checkpoints." (PMID 35571047, 2022). "First, we did not study the specific mechanism of the effect of CHSY3 on tumor proliferation and migration, which requires further research." (PMID 38812506, 2024).
CHSY3 also shares sentences with these, for which no sentence is quoted: ovarian carcinoma (2 papers); benign tumors (1); breast-invasive carcinoma (1); Cognitive impairment (1); colon adenocarcinoma (1); colorectal cancer (1); glioblastoma multiforme (1); hyperphosphataemia (1); hypophosphatemia (1); lung adenocarcinoma (1); neuroblastoma (1); oral squamous cell carcinoma (1); Pan (1); rectal cancer (1); rectum adenocarcinoma (1).